TLR9 (toll like receptor 9)
Diseases named in the same sentence as TLR9 in open-access papers (continued):
Sharing a sentence is not in itself a finding about the gene and the disease.
Sepsis (continued). "Additionally, the gain of function polymorphisms TLR9-1237T/C, rs5743836 is a risk for severe sepsis in pediatric critical care patients, with males having a higher risk and a more pronounced allele frequency of TLR9-1237T/C than females." (PMID 35956081, 2022). "In an extreme example such as massive trauma, mito-DAMPs, identified as mtDNA and formyl peptides, are acutely released from damaged tissues and cause a sepsis-like systemic inflammatory response syndrome by activating polymorphonuclear cells via TLR9 and formyl peptide receptor-129." (PMID 32398673, 2020). "Interestingly TLR9-1237T/C polymorphism is a risk factor for progression of infection to severe sepsis in patients with a male sex predisposition, which was investigated in a pediatric intensive care unit (p 0.014)." (PMID 33519463, 2020). "Previous studies have demonstrated that TLR3 and TLR9 mediate a systemic inflammatory response and contribute to cardiac dysfunction in animal models of polymicrobial sepsis, but the downstream mechanisms causing these injuries are unknown." (PMID 30364002, 2018). "TLR9-deficient mice are resistant to polymicrobial sepsis in an experimental peritonitis model." (PMID 25472474, 2014). "We hypothesized that polymicrobial sepsis induces cardiovascular dysfunction via TLR9 and thereby causes septic heart failure." (PMID 23935245, 2013). "Serum levels of TLR2, TLR4, TLR9, IL-1β, IL-6, IL-8, IL-10, TNF-α and IFN-γ were quantified by enzyme-linked immunosorbent assay at the time of sepsis diagnosis." (PMID 41846925, 2026). "In a cecal ligation and puncture (CLP)-induced sepsis model, administration of M2-EVs@DNase I significantly reduced circulating cfDNA levels by approximately 60% and suppressed TLR9 activation by about 49%." (PMID 41952672, 2026). "Recognition of bacterial PAMPs by TLRs (TLR2, TLR4, TLR5, TLR9) activates NF-κB via MyD88-dependent and -independent pathways, leading to pro-inflammatory cytokine production and potentially sepsis." (PMID 40386784, 2025). "Studies have shown that cf-mtDNA promotes inflammatory factor release and mitochondrial dysfunction in renal tubules during sepsis by activating the TLR9 signaling pathway in immune cells, particularly dendritic cells and B cells." (PMID 41327452, 2025). "As cfDNA activates inflammation by activating TLR9, clearing cfDNA or blocking the aberrant cfDNA-sensing pathway appears to be fruitful in ameliorating systemic inflammation in severe sepsis." (PMID 39811612, 2025). "However, excessive or dysregulated TLR9 activation has been implicated in sepsis-related organ injury, Thus, mitochondrial manipulation by pathogens may not only influence the cGAS-STING and NLRP3 pathways but also extend to TLR9-MyD88 signaling, further diversifying immune outcomes." (PMID 41404367, 2025). "TIRAP expression in the early stages of sepsis was in accordance with the amplification in the expression of TLR-9, indicating a possible correlation." (PMID 40076895, 2025). "Previous research proposed that inflammatory circulating cfDNA activates TLR9 is crucial for sepsis development." (PMID 39811612, 2025). "We have previously shown that adoptive transfer of a low dose of Tlr9-/–FRC (200000 FRC/mouse) improved the therapeutic efficacy in CLP-induced sepsis compared with the treatment with the same amount of WT-FRC." (PMID 38827745, 2024). "Collectively, we identify a critical role for circulating RBC TLR9 in modulating host inflammatory responses during sepsis, highlighting their dual function as both reservoirs and couriers of microbial DNA." (PMID 39666381, 2024). "To investigate the role of RBC DNA capture in sepsis, we induced CS sepsis in WT mice and mice in which Tlr9 was deleted in erythrocytes (Erytlr9–/–)." (PMID 39666381, 2024). "To understand the role of TLR9 of these FRC subsets in the therapeutic efficacy of CLP-induced sepsis, we performed adoptive transfer experiments with these FRC subsets." (PMID 38827745, 2024).
Sepsis (continued). "Our previous study showed that NETs impaired intestinal barrier function during sepsis via the TLR9‐mediated endoplasmic reticulum stress pathway." (PMID 37691112, 2024). "Using a preclinical model of sepsis and genetic deletion of erythrocyte Tlr9, we demonstrate that circulating red cell–mediated DNA delivery drives heterogeneous host inflammatory responses through DNA capture and delivery to remote organs." (PMID 39666381, 2024). "Subsequently, the cellular sepsis models were transfected with si-TLR9, and qRT-PCR and western blotting were used to determine transfection efficiency." (PMID 37085762, 2023). "Reports in the literature suggest that TLR9 inhibition substantially suppresses the excessive host inflammatory response and attenuates sepsis-induced mortality in the cecal ligation and puncture (CLP) murine model of sepsis." (PMID 37662481, 2023). "Other studies also confirmed that the occurrence of sepsis caused the significant up-regulation of TLR9, and the activation of the TLR-9-dependent pathway led to SAKI and impaired survival rate of experimental animals." (PMID 36010680, 2022). "The same group of researchers, using the CLP model, discovered that DCs activated by the TLR9/IL-17A axis have an ability to secrete IL-23, which leads to stimulation of IL-17A production in T cells during sepsis, contributing to the development of SAKI." (PMID 36010680, 2022). "Strikingly, the response to TLR9 ligand exhibits robust time-of-day variation: 1) the time-of-day determines diseases severity in a TLR9-dependent sepsis model, and 2) timing of immunization determines TLR9 ligand-adjuvanted vaccine responsiveness." (PMID 35281442, 2022). "We also observed that ISM1+ cells express TLR4, TLR5, and TLR9, and, in a mouse model of sepsis induced by P. aeruginosa, we observed that all the LSK and ISM1+LSK cells were affected." (PMID 35402623, 2022). "We have previously shown that activation of TLR9 signaling in FRCs, a subpopulation of stromal cells, suppresses chemokine production in FRCs and, thus, suppresses immune cell recruitment during sepsis." (PMID 36278484, 2022). "During polymicrobial sepsis, mtcfDNA activates TLR9 and contributes to cytokine production, splenic apoptosis, and tubular injury with mtROS overproduction." (PMID 33651717, 2021). "Their findings on a CLP model of sepsis in wild-type and TLR9-knockout mice suggest that mtDNA activates TLR9 and contributes to cytokine production and kidney injury during polymicrobial sepsis." (PMID 33732235, 2021). "Also the SNP rs187084 (T-1486C) of the TLR9 promoter previously being associated with rheumatic disease, cancers and pulmonary tuberculosis has been suggested to provide relevant risk estimates for the development of sepsis and multiple organ dysfunction in critically ill patients." (PMID 33519463, 2020). "The TLR9 activation on DCs during polymicrobial sepsis promotes the IL-17A generation from γδ T cells, which induces the sepsis-induced AKI." (PMID 33643304, 2020). "In a TLR9-dependent model of sepsis, greater lethality was observed at the time-of-day coinciding with highest TLR9 expression in splenic macrophages and B cells." (PMID 32849621, 2020). "In experimental models, TLR9 signaling is recognized as a major target for the protective actions of Chloroquine in the case of sepsis induced acute kidney injury." (PMID 33519463, 2020). "The generation of circulating mitochondrial DNA in sepsis patients and its recognition by TLR9 also induces adaptive immune cell paralysis through suppressing the CD8+ T cell function to prevent organ damage." (PMID 33643304, 2020). "Inhibition of TLR9 in mice attenuates sepsis induced mortality and provides dampening of dysregulated inflammatory markers in spleen, lung and liver." (PMID 33519463, 2020).
Sepsis (continued). "Studies performed in experimental models for polymicrobial sepsis show that circulating mtDNA via activation of TLR9, contributes to cytokine production, kidney injury during and splenic apoptosis." (PMID 33519463, 2020). "In this study, we provide novel molecular insights into the essential role of TLR9 activation in the neutrophil-dependent protection from sepsis." (PMID 31534550, 2019). "To confirm that TLR9-Cav-1 mediated sepsis protection is also translatable to patients with bacterial sepsis, we collected blood samples from patients with sepsis to characterize the protective role of TLR9-Cav-1." (PMID 31534550, 2019). "Previous studies have shown that mtDNA causes serious damage to the lungs and kidneys via TLR9 in sepsis." (PMID 31205588, 2019). "Because InP promotes the translocation of TLR9 to the cell membrane and because TLR9 is associated with Cav-1, we reasoned that Cav-1 is likely to be essential for the TLR9-mediated protective effect during sepsis." (PMID 31534550, 2019). "Membrane TLR9 expression was found to be significantly elevated among sepsis patients compared with normal donors." (PMID 31534550, 2019). "Depletion of either TLR9 or Cav-1 largely eliminates the neutrophil-mediated InP effect in sepsis models in vitro and in vivo." (PMID 31534550, 2019). "Another research on a mouse model with polymicrobial sepsis indicated that TLR9 KO mice showed significant reduction in cardiac inflammation and sustained heart function, indicating that TLR9 promotes cardiac inflammation and HF during polymicrobial sepsis." (PMID 29576748, 2018). "Our data showing lower levels of proinflammatory cytokines in the K.O. mice suggest that signaling through TLR3 and TLR9 involves release of these proinflammatory cytokines during sepsis." (PMID 30364002, 2018). "We then measured the levels of proinflammatory cytokines (IL-6 and TNF), histones, and C5a in plasma from TLR3−/−, TLR9−/−, and Wt after inducing polymicrobial sepsis by CLP." (PMID 30364002, 2018). "For this aim we performed heart functional studies in TLR3−/− and TLR9−/−, by applying Echo-Doppler technology after sepsis, to compare their responses with the septic Wt mice." (PMID 30364002, 2018). "We determined the roles of TLR3 and TLR9 in adverse events of polymicrobial sepsis, with a focus on development of septic cardiomyopathy, progression of which we have recently shown to be complement- and histones-dependent." (PMID 30364002, 2018). "We decided to study the role of TLR3 and TLR9 in the heart function during polymicrobial sepsis and proposed the role for complement C5a and histones mediating these events." (PMID 30364002, 2018). "Interestingly, the protective effect can also be seen in the TLR3- and TLR9-deficient mice against microbial challenge; and the pharmacological inhibitors of TLR9 can reduce the mortality of mice in severe sepsis and protect the host from serious complications, such as acute kidney injury." (PMID 28769820, 2017). "There are numerous studies in sepsis, trauma, and acute single-organ injury that have already demonstrated that individuals with high mtDNA levels and TLR9 expressions have worse prognosis." (PMID 28299196, 2017). "As a consequence of mitochondrial damage after sepsis, cytosolic free mtDNA fragments, potentially functioning as DAMPs to incite inflammation via TLR9, were significantly increased in the heart." (PMID 26448624, 2015). "Since free mtDNA escaped from damaged mitochondria function as a type of DAMPs to stimulate inflammation through TLR9, these data together suggest that sepsis-induced cardiac inflammation is mediated, at least partially, through mtDNA-TLR9-RAGE." (PMID 26448624, 2015). "Based on these results, we propose that sepsis-induced mtROS damage mtDNA, thus then leads to the release of free mtDNA and the activation of a TLR9 pathway, which is, at least in part, responsible for the development of cardiac failure after sepsis." (PMID 26448624, 2015).
Sepsis (continued). "The aim of our study was to analyze the expression of TLR2, TLR4 and TLR9 in patients with symptoms of sepsis after intensive induction chemotherapy for AML." (PMID 25412934, 2014). "Recently, it has been shown that polymicrobial sepsis leads to lower vascular contractility, which in turn depends mainly on TLR9 signalling." (PMID 23935245, 2013). "Sepsis was induced by i.p. application of the TLR9 agonist 1668-thioate in C57BL/6 wild type (WT) and TLR9-deficient (TLR9-D) mice." (PMID 23690658, 2013). "In polymicrobial sepsis TLR9 signalling is pivotal to cardiac inflammation and septic heart failure." (PMID 23935245, 2013). "Taken together TLR9 signalling seems to be of critical importance in polymicrobial sepsis as its absence increases survival of the animals dramatically via reduced cardiac inflammation." (PMID 23935245, 2013). "Herein, we will review the most popular agonist (TLR3, TLR5, TLR7, TLR8, TLR9) and antagonist (TLR2, TLR3, TLR4, TLR9) agents used in pre-clinical and clinical models of acute and chronic infections, including sepsis." (PMID 24302927, 2013). "As a proof of concept, administration up to 12 h after surgery of a single dose of an inhibitory CpG ODN blocking TLR9 signaling protected mice from polymicrobial sepsis following CLP." (PMID 24302927, 2013). "TLR9 signaling revealed to be decisive during polymicrobial sepsis as vascular tone of TLR9-D mice remained unaffected while that of WT, TLR2-D, and TLR4-D mice was significantly reduced." (PMID 22970242, 2012). "For the first time, we explored TLR2, TLR4 and TLR9 expression on and in human blood NK cells during sepsis." (PMID 23098236, 2012). "Our results complement the finding of Yasuda and colleagues, that TLR9-antagonism was suitable to reduce sepsis-induced kidney failure." (PMID 22970242, 2012). "There is evidence in the literature, that TLR9 is crucial for the induction of polymicrobial sepsis." (PMID 22970242, 2012). "DNA-sequence analyses and studies with Toll-like receptor 9 (TLR9) reporter cells suggests that the cfDNA from sepsis patients is host derived." (PMID 22889177, 2012). "In studies focusing on infection or sepsis, associations have been described for SNPs in the TLR1 (rs5743551), TLR2 (rs5743708), TLR4 (rs4986790 and rs4986791), TLR9 (rs5743836), IRAK1 (rs1059703), and TIRAP genes (rs8177374 and rs7932766)." (PMID 21219635, 2011). "Five genes, namely TLR2, TLR4, TLR9, MyD88 and TOLLIP, were investigated for their association with sepsis susceptibility by a tag single nucleotide polymorphism (SNP) strategy." (PMID 21219635, 2011). "Among them, TLR2, TLR4, and TLR9 have been established to play a key role in the mediation of systemic responses to invading pathogens during sepsis." (PMID 21219635, 2011). "The data presented here are consistent with a functional impairment of TLR4 and TLR9 agonist-induced cellular responses in MDCs and PDCs in patients with sepsis." (PMID 19604380, 2009). "Previous studies have indicated that TLR9 has a detrimental effect on cardiac function during sepsis, and another study reported that TLR9/Caveolin-1 signaling may help predict treatment outcomes in sepsis patients." (PMID 39861004, 2025). "In addition, the expression of TLR-9 in lung tissue was mainly induced after 48 h with a continuous upward trend, indicating a possible direct correlation with ongoing sepsis and acute lung injury." (PMID 40076895, 2025). "Similarly, zinc‐based nanoparticles have shown great promise in targeting TLR9 and reducing both inflammation and bacterial load, providing a multifunctional approach to sepsis treatment." (PMID 40599085, 2025). "Then we elucidate how cfDNA contributes to the development of sepsis and investigate whether cfDNA-mediated TLR9 pathway activation results in the release of proinflammatory cytokines during sepsis." (PMID 39811612, 2025). "When compared with the normal group, the sepsis group's serum TLR9 levels were statistically lower." (PMID 38685971, 2024).
Sepsis (continued). "Moreover, CQ has demonstrated effectiveness as an acute systemic infection pathology and TLR9 blocker in experimental models of polymicrobial sepsis." (PMID 38358825, 2024). "RBCs from the Erytlr9–/– mice did not acquire additional microbial DNA after CS injection, suggesting that RBCs may have acquired microbial DNA during sepsis through Tlr9." (PMID 39666381, 2024). "In addition, we have previously demonstrated that critically ill patients with sepsis demonstrate elevated surface RBC TLR9 and diversity in surface RBC TLR9 expression." (PMID 39666381, 2024). "In addition, in the TLR9-dependent septicemia model, stronger lethality was observed on the day when TLR9 expression was highest in spleen macrophages and B cells." (PMID 38678017, 2024). "Notably, mtDNA can also serve as a metabolic-associated molecular marker that accelerates the progression of sepsis through the Toll-like receptor 9 (TLR9)-NLR family pyrin domain containing 3 signaling pathways." (PMID 39164792, 2024). "TLR9 inhibition in-vivo by gene deletion, small interfering RNA, and chemical inhibitors such as chloroquine have been shown to significantly reduce the sepsis-related inflammatory response in animal models." (PMID 37662481, 2023). "Moreover, Liu and colleagues nicely proved that exosomal miR-342-5p derived from MSCs had the ability to mitigate acute kidney injury by inhibiting TLR9 in a sepsis mouse model." (PMID 37626949, 2023). "Accumulating evidence has revealed that TLR9 contributes to the development of sepsis-related AKI." (PMID 37085762, 2023). "Previous studies have demonstrated the effect of TLR9 inhibition on sepsis survival." (PMID 37662481, 2023). "Inhibition of the responses against bacterial DNA by TLR-9 inhibition could attenuate LPS-DNA synergy in macrophages and might help improve sepsis hyper-inflammation in some situations." (PMID 35163830, 2022). "Previous studies has been reported that NETs could upregulated TLR9 expression in sepsis and sepsis lung injury 3,21,27." (PMID 35637949, 2022). "In a cecal ligation and puncture model of sepsis, knockout (KO) of TLR-9 attenuated renal injury and reduced leukocyte migration, suggesting that TLR-9 depletion may facilitate the inhibition of inflammation." (PMID 33644078, 2021). "The activation of innate immune receptors by fungi generally follows the same pattern as bacteria, with TLR2, TLR4, TLR9 and NLRP3 being common to the fungi (Aspergillus, Candida and Cryptococcus species) most often associated with COVID-19, ALI/ARDS and sepsis." (PMID 33672738, 2021). "The TLR9 inhibition during polymicrobial sepsis may protect from sepsis-induced AKI and immunosuppression." (PMID 33643304, 2020). "Thus far, we showed that TLR9 and Cav-1 interaction is critical for the protective effect of InP against sepsis, but it was unclear how these molecules interact with one another." (PMID 31534550, 2019). "Therefore, our results indicated that membrane TLR9-Cav-1 is activated in the setting of bacterial sepsis, and that upregulation was correlated with improved clinical outcomes among patients with sepsis." (PMID 31534550, 2019). "Collectively, these findings suggest that TLR9-Cav-1 signaling could be a powerful indicator of therapeutic outcome in patients with sepsis." (PMID 31534550, 2019). "Our finding suggests that TLR9/Cav-1 signaling might be useful for predicting therapeutic outcomes in patients with sepsis." (PMID 31534550, 2019). "This is contrary to the traditional view that TLR9 is an important injury factor in sepsis." (PMID 31205588, 2019). "Also TLR9−/− mice showed attenuated septic cardiomyopathy and a significant reduction of cardiac inflammation after sepsis." (PMID 30364002, 2018). "The harmful effects of TLR3 or TLR9 on cardiac dysfunction during sepsis have been reported." (PMID 30364002, 2018). "Importantly, mtDNA contributes to the activation of Toll-like receptor 9 and inflammasomes, propagating damage to distant organs following sepsis." (PMID 29682165, 2018).